ADCY8 (adenylate cyclase 8)
Diseases named in the same sentence as ADCY8 in open-access papers (continued):
Sharing a sentence is not in itself a finding about the gene and the disease.
melanoma (2 papers, 2018 to 2020). A malignant, usually aggressive tumor composed of atypical, neoplastic melanocytes. "ADCY8 mutations were previously identified in melanoma patients." (PMID 32241263, 2020).
amnesia (1 paper, 2024). Pathologic partial or complete loss of the ability to recall past experiences ( AMNESIA, RETROGRADE) or to form new memories ( AMNESIA, ANTEROGRADE). "Adenylate cyclase 8 (ADCY8) functions in the regulation of synapse activity and has been associated with dissociative amnesia." (PMID 39062924, 2024).
autism spectrum disorder (1 paper, 2022). A spectrum of developmental disorders that includes autism, and Asperger syndrome. "Further, an integrative analysis of brain transcriptome in autism spectrum disorder and genomic variants in obsessive-compulsive disorder identifies Adcy8 as a common risk factor for autism spectrum disorder and obsessive-compulsive disorder." (PMID 36188604, 2022).
Hepatitis C (1 paper, 2021). "Another gene in the hsa04550 pathway, GRB2, coding for Growth Factor Receptor Bound Protein 2, is associated with Hepatitis C and Hepatitis E. In turn, Calmodulin-activated adenylate cyclases (ADCY1 and ADCY8 genes) generate cAMP." (PMID 35008650, 2021).
lung adenocarcinoma (1 paper, 2023). A carcinoma that arises from the lung and is characterized by the presence of malignant glandular epithelial cells. "The low expression of ADCY8 is correlated with poor overall survival and progression-free survival in lung adenocarcinoma." (PMID 37511481, 2023).
lung carcinoma (1 paper, 2021). "Moreover, all of the eight novel hypermethylation driver genes (PCDH17, IRX1, ITGA5, HSPB6, TBX5, ADCY8, GALNT13 and TCTEX1D1) were successfully validated in an independent cohort via a pyrosequencing approach, with an AUC of 0.965 for prediction of lung cancer patients." (PMID 33859751, 2021). "The remaining eight genes are newly identified methylation drivers in lung cancer, including 5 known cancer methylation driver genes in other cancer types (HSPB6, IRX1, ITGA5, PCDH17, TBX5) and 3 novel genes that had not been previously reported (ADCY8, GALNT13 and TCTEX1D1)." (PMID 33859751, 2021).
lung squamous cell carcinoma (1 paper, 2025).
osteosarcoma (1 paper, 2024). A usually aggressive malignant bone-forming mesenchymal neoplasm, predominantly affecting adolescents and young adults. "We initially compared the gene set expression between male and female WT mice, finding a significant reduction, albeit below a fold change of 2.5, in the expression levels of two genes in males compared to females - Fos (FBJ osteosarcoma oncogene) and Adcy8 (Adenylate cyclase 8)." (PMID 39583831, 2024).
pancreatic tumors (1 paper, 2019). "In pancreatic tumors, for example, GNAS SWI arginine and p.V633M mutations in the downstream adenylate cyclase ADCY8 are mutually exclusive in addition to those affecting DRY Arginine of upstream GPCRs." (PMID 31337866, 2019).
posttraumatic stress disorder (1 paper, 2022). "A GWAS study implicates a suggestive association of Adcy8 with posttraumatic stress disorder." (PMID 36188604, 2022).
pulmonary fibrosis (1 paper, 2020). Chronic progressive interstitial lung disorder characterized by the replacement of the lung tissue by connective tissue, leading to progressive dyspnea, respiratory failure, or right heart failure. "To validate the effect of AS on the expression of the five key genes (ADCY1, ADCY5, ADCY8, cAMP and Rap1) in cAMP and Rap1 signal pathways in pulmonary fibrosis, we measured their expression at gene level and protein level by RT‐qPCR and ELISA experiments, respectively." (PMID 32548952, 2020). "Based on above findings, we further identified key genes (ADCY1, ADCY5, ADCY8) in cAMP signal pathway and Rap1 signal pathway which were potentially regulated by the treatment of AS in BLM‐induced pulmonary fibrosis." (PMID 32548952, 2020).
Stroke (1 paper, 2015). Sudden impairment of blood flow to a part of the brain due to occlusion or rupture of an artery to the brain. "Finally, the potential of rTMS in promoting neuroprotection and plasticity in stroke is further corroborated by the results that showed a significant increase in expression of genes involved in GPCR signaling (Arrb1, Adcy8 and Bdnf)." (PMID 26431529, 2015).
viral infection (1 paper, 2023). "The down-regulation of Adcy8 observed in our study indicates the potential alternation of PNS functions by viral infection and the effect of lung innervation in the host response to IAV infection." (PMID 38005876, 2023).
cancer (15 papers, 2014 to 2024). A tumor composed of atypical neoplastic, often pleomorphic cells that invade other tissues. "We further analyzed the variation and methylation of GLP-1 signaling-related genes, which suggesting ADCY8 had the highest mutation rate in single nucleotide mutations and was inclined to be hypermethylated in pan-cancer." (PMID 39104385, 2024). "A number of known and previously unknown oncogenes were identified, some of which have already been reported to be associated with cancer, including: ADCY8, ZFAT, BAI1, PTK2, FBXL6, FOXH1, HSF1, and UGT2A1." (PMID 25372838, 2014). "As for methylation, GNGT1, KCNS3, GCG and PPKACG tended to be hypomethylated in pan-cancer while ADCY8 tended to be hypermethylated." (PMID 39104385, 2024). "We observed that 18 genes revealed a significant negative correlation (FDR < 0.01, Spearman's rho < -0.3) in at least five cancer types, except for ADCY8 and TBX5, which showed a cancer-type specific methylation driver." (PMID 33859751, 2021). "Published literature on promoter methylation of ADCY8, CDH8, and ZNF582 has expanded recently and hypermethylation of one or more of these loci have been found in cancers of the breast, oropharynx, esophagus, and anus." (PMID 33178175, 2020). "For example, AGTR1, GRIN2A, ITPKB, and SLC8A3 were repressed by hypermethylation in six cancer types, and ADCY4, ADCY8, BST1, and PRKCB were inhibited by hypermethylation in five cancer types." (PMID 28060724, 2017). "To validate these results, based on the 340 epigenetically silenced genes in at least five cancer types, we drew a protein-protein interaction network and found some genes with higher degrees of interaction, such as ADCY4, ADCY8, and PRKCB.." (PMID 28060724, 2017). "The genes which have been reported to involve the cancer cell invasion (ENPP2, ADCY8), dysregulated cellular metabolism (CYC1), and angiogenesis (ANGPT1), immune inhibition (ANXA3) amplified notably in the high-risk group, which might elaborate the aggressiveness and malignancy in this group." (PMID 34568069, 2021).
tumor (10 papers, 2016 to 2025). "Furthermore, we omitted variant rs10956571 within Adenylate Cyclase 8 (ADCY8) from further evaluations because the variant displayed significance only in the PTC tumor training set and PTC blood validation set." (PMID 39770638, 2024). "Future studies should aim to perform functional experiments, such as Transwell invasion assays, siRNA‐mediated knockdown, overexpression studies, and in vivo metastasis models, to establish a direct mechanistic link between ADCY8 and tumor progression." (PMID 40095726, 2025). "We found that gap junction signaling pathways (ADCY8 and PPP1R9A) were upregulated and cell adhesion signaling pathways (VSIR and HLA-C) were downregulated, which is associated with tumor growth metastasis." (PMID 37511481, 2023). "Promoter methylation of four candidate tumor suppressor genes (adenylate cyclase 8 (ADCY8), cadherin 8, type 2 (CDH8), MGMT, and zinc finger protein 582 (ZNF582)) out of 48 genes screened was quantified by bisulfite-pyrosequencing of genomic DNA." (PMID 27651839, 2016). "Furthermore, except for ADCY8, the up-expression of above genes were all related to tumor development, metastasis, invasion, sensitivity to radiotherapy and chemotherapy or prognosis." (PMID 35668376, 2022). "Interestingly, except for ADCY8, the up-expression of above genes were all significantly related to tumor development, metastasis, invasion, sensitivity to radiotherapy and chemotherapy or prognosis." (PMID 35668376, 2022). "Taken together, ADCY8, CDH8, and ZNF582 promoter methylation are promising predictive and prognostic biomarkers for multiple tumor types crossing geographic and racial boundaries that undeniably merits further validation." (PMID 33178175, 2020). "Therefore, ADCY8 and HSPG2 were selected as the most promising candidates from this double germline–tumor disrupting SNV approach." (PMID 30871259, 2019). "However, increased median methylation (~10×) of ADCY8, CDH8, and ZNF582, but not MGMT, was noted in the tumor cohort (N = 257) compared with the three normal samples." (PMID 27651839, 2016).
metabolic disorders (1 paper, 2022). "Studies have shown that ADCY8 induces innate immune-associated antiviral host defense in response to macrophage SCN5A, and ADCY8 also affects glucagon-like peptide 1 signaling and glucose levels in metabolic diseases." (PMID 36532504, 2022).
ADCY8 also shares sentences with these, for which no sentence is quoted: type 2 diabetes (5 papers); schizophrenia (3); hyperglycaemia (2); Insulin resistance (2); mental disorder (2); neurodegenerative disease (2); neurological diseases (2); Parkinson disease (2); Alzheimer disease (1); anxiety disorder (1); atherosclerosis (1); atrial fibrillation (1); autoimmune thyroid disease (1); behavioral anxiety (1); brain tumor (1); breast adenocarcinoma (1); café-au-lait macules (1); chronic kidney disease (1); chronic liver failure (1); diabetic nephropathy (1); dissociative amnesia (1); epilepsy (1); gastric cancer (1); glaucoma (1); Hepatitis (1); Hypertension (1); hypertrophic cardiomyopathy (1); infarction (1); infection (1); injury (1).
A further 15 diseases each share a sentence with ADCY8 in 1 paper.